H19 (H19 imprinted maternally expressed transcript)
Diseases named in the same sentence as H19 in open-access papers (continued):
Sharing a sentence is not in itself a finding about the gene and the disease.
endometriosis (continued). "Similarly, there are no studies concerning the top 10 dysregulated lncRNAs in endometriosis, but the DElncRNA H19 has been reported as an efficient regulator in altering stromal cell growth via IGF signaling pathway in the endometriosis." (PMID 32112646, 2020). "In addition, it has been reported that H19 can function as a molecular sponge of let-7 and H19/Let-7/IGF1R regulatory pathway may related with impaired endometrial preparation and receptivity for pregnancy in women with endometriosis." (PMID 27580177, 2016). "Given that women with unexplained infertility show decreased H19 expression in their eutopic endometrium and that H19 regulates let-7 which targets Igf1r, we wished to determine the physiological role of H19 in the endometrium and its relationship with the IGF signaling in endometriosis." (PMID 26089099, 2015). "For example expression of H19, a well known, imprinted, long-non coding RNA, was high in OSEC11 but absent in EEC16, which may suggest a role for H19 in endometriosis development." (PMID 24502583, 2014). "In addition to H19’s established role in promoting cell growth, proliferation, invasion, migration, epithelial–mesenchymal transition (EMT) and metastasis, H19 has recently been discovered to inhibit programmed cell death (PCD) of cancer cells.Endometriosis is not classified as a malignant neoplasm." (PMID 38791310, 2024). "In this case–control study, 24 women with and without endometriosis were studied for the relative expression of VEGF, IGF1, IGF2 and H19 lncRNA genes using real-time polymerase chain reaction (PCR) technique." (PMID 35459174, 2022).
cardiac hypertrophy (38 papers, 2009 to 2025). "LIN28A interacts with lncRNA H19 to enhance its expression and influence stem cell dynamics, potentially mitigating heart failure caused by cardiac hypertrophy." (PMID 39334823, 2024). "In addition, the expression of lncRNA H19 and its encoded miR-675 were verified to be up-regulated in pathological cardiac hypertrophy and HF." (PMID 34692796, 2021). "H19 is associated with regulation of a low fat-free mass, cardiac hypertrophy, and apoptosis." (PMID 28837672, 2017). "Interestingly, H19 also encodes for the small ncRNA miR-675 that is embedded in the H19 locus and that can target Ca2+/calmodulin-dependent protein kinase IIδ (CaMKIIδ), a powerful inducer of cardiac hypertrophy." (PMID 39086960, 2022). "Functionally, long non-coding RNA H19 (lncRNA H19) plays a crucial role in alleviating pathological cardiac hypertrophy by regulating genes involved in cardiac remodeling." (PMID 39334823, 2024). "A recent study reported that targeting LncRNA H19 can reverse pathological cardiac hypertrophy by interacting with polycomb repressive complex 2 (PRC2) to control the nuclear factor of activated T-cells (NFAT) signaling." (PMID 37253771, 2023). "Another study showed that H19 expression was up-regulated in a mouse model of pathological cardiac hypertrophy and HF induced by transverse aortic constriction (TAC)." (PMID 35946958, 2022). "For instance, overexpression of lncRNA H19 up-regulated of miR-675 expression and H19-miR-675 axis played an important role in cardiac hypertrophy by targeting CaMKIIδ." (PMID 35091561, 2022). "The role of H19 in cardiac hypertrophy has been previously investigated in both mouse and pig models of cardiac hypertrophy in human samples and cell cultures." (PMID 35139769, 2022). "We have demonstrated recently that AAV9-based delivery of the long non-coding RNA (lncRNA) H19 reverses pathological cardiac hypertrophy in the TAC mouse model." (PMID 35810332, 2022). "H19 is upregulated at the early phase of pressure overload-induced cardiac hypertrophy but is downregulated at later stages." (PMID 35461308, 2022). "Subsequent studied demonstrated that H19 is upregulated in pathological forms of cardiac hypertrophy and heart failure." (PMID 39086960, 2022). "H19 expression analysis after heart explantation showed the expected decrease in endogenous H19 in cardiac hypertrophy." (PMID 35810332, 2022). "For instance, H19 and RMRP are involved in heart failure progression, while BDNF-AS is a cardiomyocyte damage-associated gene; SNHG7 is a cardiac hypertrophy regulator." (PMID 35415316, 2022). "lncRNAs H19 is strongly involved in heart disorders and the role of H19 in cardiac hypertrophy has been previously investigated in mouse models, human samples and cell cultures." (PMID 35139769, 2022). "In pressure overload-induced left ventricular hypertrophy mice, H19 ablation aggravates cardiac hypertrophy compared to wild-type mice." (PMID 34604357, 2021). "The results disclosed that XIST, MALAT1 and H19 possibly regulated other miRNAs involved in cardiac hypertrophy, such as miR-15b, miR-19b and miR-29b in our research." (PMID 34362365, 2021). "For example, a conserved lncRNA H19 represses cardiac hypertrophy by preventing and reversing experimental pressure-overload-induced heart failure, and Duchenne and Becker muscular dystrophy associated cardiomyopathy." (PMID 34604357, 2021). "Murine and human lncRNA H19 display an anti-hypotrophy function, and CM-restricted H19 gene delivery can suppress the development of cardiac hypertrophy and later on heart failure." (PMID 34604357, 2021). "Consistently, all those studies reported that overexpression of H19 in CMs can mitigate cardiac hypertrophy." (PMID 34604357, 2021). "H19 has been well-studied in heart development and various heart diseases, including diabetic cardiomyopathy, myocardial infarction, cardiac hypertrophy, muscular dystrophies and heart failure." (PMID 34604357, 2021).
cardiac hypertrophy (continued). "Overall, the enforced expression of H19 up‐regulated miR‐675 expression and reduced cardiomyocyte dimensions in pathological cardiac hypertrophy, whereas H19 or miR‐675 knockdown reversed these effects." (PMID 33052009, 2020). "A novel study reveals that H19 functions as a negative regulator in pathological cardiac hypertrophy mediated by miR-675." (PMID 28287427, 2017). "Intriguingly, among the conserved lncRNAs, h19, rmrp and hotair were also induced in a mouse model of heart hypertrophy." (PMID 27317124, 2016). "Here we showed the increase of H19 levels in HF patients, both end-stage and non, and confirmed its upregulation in a mouse model of cardiac hypertrophy." (PMID 27317124, 2016). "Several cases of striking cardiac hypertrophy were noted but this was probably related to the genetic background or the defect in H19, also being seen in the H19+/− maternal line on an Sdhd wt background." (PMID 19956719, 2009). "The lncRNA H19-miR-675-CaMKIIδ axis negatively regulates the progression of cardiac hypertrophy." (PMID 40874024, 2025). "Another study revealed a cardioprotective role for H19 against cardiac hypertrophy." (PMID 36768528, 2023). "H19 knock-out mice had worse cardiac hypertrophy after pressure overload." (PMID 37259407, 2023). "Additionally, in vivo experiments in murine, porcine, and human engineered heart tissue (hEHT) models of cardiac hypertrophy demonstrated the anti-hypertrophic benefits of H19." (PMID 36768528, 2023). "For example, LncRNA H19 is dysregulated in pathological cardiac hypertrophy models." (PMID 37253771, 2023). "In addition, mouse, pig, and engineered heart tissue models of cardiac hypertrophy also demonstrate the anti-hypertrophic benefits of H19." (PMID 37762106, 2023). "We would prove that H19 suppresses cardiac hypertrophy through the MicroRNA-145-3p/SMAD4 axis." (PMID 35139769, 2022). "H19 sponges miR-675 to target CaMKIIδ as a negative regulator of cardiac hypertrophy." (PMID 35990951, 2022). "H19 knockout promotes cardiac hypertrophy, while H19 overexpression inhibits cardiac hypertrophy." (PMID 35461308, 2022). "H19 repression was also observed in a pig model of cardiac hypertrophy and diseased human hearts." (PMID 35461308, 2022). "Moreover, repression of H19 was observed in the heart of a pig model of cardiac hypertrophy and in human tissue." (PMID 35946958, 2022). "Here, H19 also acted as a host gene for miR-675, which displays the same expression pattern as H19 and was demonstrated to repress its downstream target prohypertrophic gene CaMKIIδ, leading to attenuation of cardiac hypertrophy and improved function." (PMID 35946958, 2022). "Furthermore, the size of cardiomyocytes increased in H19-overexpressing mice at day 4 post-MI, suggesting that the overexpression of H19 indeed has an effect on cardiac hypertrophy." (PMID 34344446, 2021). "(iv) Does H19 act on both myocardial cells and fibroblasts to regulate myocardial hypertrophy?" (PMID 34344446, 2021). "Furthermore, we observed a slight increase in the size of cardiomyocytes in H19OE mice post-MID4, suggesting the overexpression of H19 indeed has a mild effect on cardiac hypertrophy." (PMID 31588235, 2019). "Finally, Ca2+/calmodulin-dependent protein kinase II δ-isoform (CaMKIIδ) has been identified to be a direct target of H19/miR-675 axis, which is involved in the regulation of cardiac hypertrophy." (PMID 28287427, 2017). "Besides, H19 has been identified as a regulator that targets PPARα of cardiac hypertrophy." (PMID 34362365, 2021). "In addition, H19 inhibition was found to decrease human umbilical vein endothelial cells (HUVEC) growth and capillary formation, while the H19-miR-675 axis targets calcium/calmodulin dependent protein kinase II Delta (CaMKIIδ), thus serving as a negative regulator of cardiac hypertrophy." (PMID 28670289, 2017).
cardiac hypertrophy (continued). "Both H19 and RMRP engage in cardiac hypertrophy and heart failure progression, while a BDNF-AS downregulation can activate BDNF, VEGF, and Akt, and thus rescue hypoxia/reoxygenation-induced damage in cardiomyocyte." (PMID 35415316, 2022). "By analogy, we packaged H19 into AAV9, AAV2-THGTPAD, and AAV2-NLPGSGD and injected mice 4 weeks after induction of TAC, i.e., when cardiac hypertrophy had already developed." (PMID 35810332, 2022). "Intriguingly, cardiac hypertrophy was augmented in H19 knockout mice following TAC as compared with wild-type littermates, and cardiac-specific overexpression of H19 via vector-based gene therapy ameliorated cardiac dysfunction of TAC-operated mice." (PMID 35946958, 2022). "For example, lncRNA H19 and lncRNA-ROR promote cardiac hypertrophy." (PMID 35711309, 2022). "Besides AHIT, lncRNA H19, increased in the myocardial hypertrophy mouse model, has also been determined to inhibit H3K27 trimethylation, which in turn reverses pathological cardiac hypertrophy." (PMID 37762106, 2023). "Under cardiac hypertrophy, H19 acts as a miR-675 precursor to regulate the expression of miR-675 downstream gene VDAC1 and CM apoptosis in cytoplasm; In nucleus, H19 regulates PRC2 occupancy on the promoters of DIRAS3 and Tescalcin to repress cardiac hypotrophy." (PMID 34604357, 2021). "Cardiac hypertrophy in neonatal LOI mice is mediated by circulating IGF2 activation of AKT/mTOR signaling in cardiomyocytes and is independent of H19 gene function." (PMID 34402430, 2021).
Silver-Russell syndrome (36 papers, 2009 to 2026). Silver-Russell syndrome is characterized by growth retardation with antenatal onset, characteristic facies and limb asymmetry. "For instance, demethylation of H19 was associated with growth-related syndromes in human: hypomethylation of H19 being described in Silver-Russell Syndrome, characterized by severe intrauterine and postnatal growth retardation among other clinical features." (PMID 29698523, 2018). "This is in contrast to patients with Beckwith-Wiedemann or Silver-Russell syndrome where both the H19-ICR and IGF2-DMR display a gain or loss of methylation, respectively." (PMID 21991322, 2011). "A loss of methylation at the H19 DMD in humans is found in a subset of Silver Russell syndrome (SRS) cases." (PMID 20617174, 2010). "In addition, we found that imprinted genes in the H19/Igf2 cluster associated with Beckwith-Wiedemann and Silver-Russell syndromes (BWS & SRS) were dysregulated." (PMID 24818964, 2014). "Silver-Russell syndrome (SRS) is a disorder characterized by intrauterine growth retardation and severe postnatal growth retardation, and is caused by epimutation of the H19 gene in the 11p15.5 region." (PMID 22735547, 2012). "In Silver-Russell Syndrome (SRS) Hypomethylation of the H19/IGF2 imprinted domain on chromosome 11p15 accounts for 50–60% of cases of Silver-Russell Syndrome (SRS), while maternal uniparental disomy of chromosome 7 (MatUPD7) is found in about 10% of cases." (PMID 40730975, 2025). "IGF2, as well as the H19 gene, when hypomethylated at the ICR1 locus, are associated with Silver-Russell syndrome." (PMID 34356068, 2021). "Their deregulated expression is the cause of Beckwith–Wiedemann syndrome (H19, IGF2, KCNQ1OT1), Russel-Silver syndrome (H19, IGF2, KCNQ1OT1) and Uniparental disomy 14 (MEG3) and is also observed in several tumors." (PMID 31143763, 2019). "Hypomethylation of the paternal allele of the H19 ICR is associated with the pre- and postnatal growth disorder Silver-Russell syndrome (SRS; OMIM 180860)." (PMID 30808399, 2019). "The IGF2 locus is used in clinical diagnostic settings to identify Beckwith-Wiedemann syndrome, which is characterized by overgrowth, and the H19 locus has been used in the diagnosis of Silver-Russell syndrome (SRS), which is characterized by undergrowth." (PMID 29988473, 2018). "Loss of paternal methylation (LOM) of the H19/IGF2 intergenic differentially methylated region (H19/IGF2:IG-DMR) causes alteration of H19/IGF2 imprinting and Silver-Russell syndrome (SRS)." (PMID 29484033, 2018). "The in vitro analysis of the hypomethylation of imprinting control region 1 (ICR1) within the IGF2/H19 locus is challenged by the mosaic distribution of the epimutation in tissues from children with Silver-Russell syndrome (SRS)." (PMID 25657826, 2015). "We generate model mice for Silver-Russell syndrome (SRS), an imprinting disorder, by target-specific DNA demethylation in the H19 differentially methylated region." (PMID 32234052, 2020). "Dysregulation of the imprinted H19/IGF2 locus can lead to Silver-Russell syndrome (SRS) in humans." (PMID 36441651, 2022). "Imprinting disorders have shown the importance of the adequate H19 ICR methylation: hypomethylation results in downregulation of IGF2 and biallelic expression of H19, leading to a growth restriction disorder, Silver-Russell syndrome." (PMID 29946374, 2018). "H19/IGF2 with copy number variations, located on the 11p15 imprinted region, was reported in Beckwith-Wiedemann and Silver-Russell syndromes." (PMID 25058480, 2014). "Silver-Russell syndrome (SRS), mainly driven by IGF2 / H19 imprinting domain hypomethylation in the 11p15 region, is characterized by IUGR and short stature due to catch-up growth failure." (PMID 38763958, 2024).
infertile (35 papers, 2013 to 2025). "Previous research links methylation abnormalities in lncRNA H19 to MTHFR gene dysfunction in infertile men, while another study associates lncRNA HOTAIR with chemoresistance in esophageal cancer." (PMID 39026221, 2024). "First, this is a meta-analysis of cross-sectional studies, which is why a direct cause-and-effect relationship between H19 gene methylation levels and infertility cannot be established." (PMID 37108386, 2023). "Hypomethylation of H19 has been associated with oligozoospermic, asthenozoospermic, and teratozoospermic infertile males." (PMID 38136954, 2023). "Within the limitations of the published data of variable quality, our meta-analysis suggests the potential causal role of reduced levels of H19 gene methylation in the pathogenesis of infertility, particularly in patients with oligozoospermia." (PMID 37108386, 2023). "A meta-analysis reported that as compared to the H19 methylations in the sperm DNAs of fertile men, there was almost ten-fold higher risk ratio of aberrant H19 methylation in the sperm DNAs of infertile men." (PMID 36357889, 2022). "Loss of methylation at DMRs of both IGF2 and H19 at variable CpG positions is correlated with an increase in abnormal sperm and infertility in men." (PMID 36061209, 2022). "Altered methylation in H19 has been broadly documented to be associated with infertile males affected by oligozoospermia, asthenozoospermia, teratozoospermia, OA, AT, and OAT." (PMID 34368137, 2021). "Intriguingly, gain of methylation at mICRs (e.g., KCNQ1OT1, MEST, PLAGL1 and SNRPN) and loss of methylation at pICRs (e.g., H19) are frequently observed in spermatozoa from infertile human patients." (PMID 27880848, 2016). "There is significant association between male factor infertility and alterations in sperm DNA methylation, especially at the H19 imprinted locus." (PMID 24015185, 2013). "Also, a significantly lower H19 methylation rate was found in patients with idiopathic recurrent pregnancy loss and infertile patients, compared to fertile men." (PMID 38717684, 2025). "Furthermore, hypermethylation of the paternally imprinted gene H19 has been linked with promoter hypermethylation of the MTHFR gene in sperm DNAs from infertile males." (PMID 38136954, 2023). "We discovered two lncRNAs associated to infertility in the LncRNADisease database: H19 and NEAT1." (PMID 35419445, 2022). "Actually, 100% methylation of the H19 imprinting control area was shown in normal individuals, while H19 was hypomethylated in diabetic infertile males." (PMID 40141439, 2025). "A meta-analysis showed that sperm’s H19 differently methylated region (DMR) methylation levels were significantly lower in infertile than fertile males." (PMID 39017772, 2024). "100% methylation of the H19 imprinting control area (ICR) is shown in normal individuals, while H19 hypomethylation is shown in diabetic infertile males." (PMID 38225568, 2024). "The disappearance of the relationship between IGF2 expression and IGF2AS and H19 methylations in the infertile group provides new information regarding the disruption of epigenetic programming during spermatogenesis." (PMID 39017772, 2024). "This would seem to confirm the direct role, not mediated by alterations to the sperm parameters (namely, sperm concentration), of alterations in the methylation of the H19 gene on the pathogenesis of infertility." (PMID 37108386, 2023). "In this systematic review and meta-analysis, we demonstrated that patients with infertility and/or abnormal sperm parameters have reduced H19 gene methylation levels compared to fertile men and/or men with normal sperm parameters." (PMID 37108386, 2023). "There is now enough convincing evidence from various sources to make the case that lncRNA H19 is an important factor impacting infertility." (PMID 37507391, 2023).